RIMS3 (regulating synaptic membrane exocytosis 3)
Description:
Regulates synaptic membrane exocytosis.
Synonyms: Nim3; RIM 3; RIM3
Tractability: PROTAC: ubiquitination databases record sites on it; its protein half-life has been measured.
Gene: Protein-coding gene on chromosome 1 (40,620,679 to 40,665,690, reverse strand). Ensembl gene ENSG00000117016.
Subcellular location: Synapse
Subcellular location (Human Protein Atlas): Mitochondria; Nucleoli; Nucleoplasm
Gene Ontology:
Molecular function: protein binding; structural constituent of presynaptic active zone; transmembrane transporter binding; small GTPase binding
Biological process: calcium-ion regulated exocytosis; regulation of membrane potential; regulation of synaptic vesicle exocytosis; synaptic vesicle priming; exocytosis; maintenance of presynaptic active zone structure
Cellular component: presynaptic active zone; presynaptic active zone cytoplasmic component; presynaptic membrane; membrane; synapse
Genetic constraint (gnomAD): Loss-of-function variants: 15 observed, 30.96 expected, observed/expected ratio (o/e) 0.48, 90% interval 0.32 to 0.75. The upper end of that interval is the gene's LOEUF score, 0.75, which puts it in group 3 of 6, group 1 being the genes least tolerant of losing a copy. Missense variants: 342 observed, 435.15 expected, observed/expected ratio (o/e) 0.79, 90% interval 0.72 to 0.86. Synonymous variants: 161 observed, 176.37 expected, observed/expected ratio (o/e) 0.91, 90% interval 0.8 to 1.04.
Homologues: Orthologues: chimpanzee RIMS3 (100% identical), macaque RIMS3 (98% identical), guinea pig RIMS3 (97% identical), mouse Rims3 (97% identical), rat Rims3 (96% identical), rabbit RIMS3 (96% identical), pig RIMS3 (92% identical), tropical clawed frog rims3 (82% identical), dog RIMS3 (78% identical), zebrafish rims3 (77% identical), Drosophila melanogaster Rim (42% identical), Caenorhabditis elegans unc-10 (37% identical). Paralogues in human: RIMS1 (67% identical), RIMS2 (66% identical), RIMS4 (47% identical), NANOGNB (8% identical).
Diseases named in the same sentence as RIMS3 in open-access papers:
RIMS3 is named in the same sentence as 10 diseases in open-access papers, as found by Europe PMC text mining. Sharing a sentence is not in itself a finding about the gene and the disease. The quoted sentences say what the papers report.
autism (6 papers, 2013 to 2022). Persistent deficits in social interaction and communication and interaction as well as a markedly restricted repertoire of activity and interest as well as repetitive patterns of behavior. "Some of these genes code for synaptic proteins such as the active zone protein Rims3, which has been associated with autism and schizophrenia." (PMID 25981962, 2015). "No study so far has reported the association of RIMS2 with genetic disorders, but its homologues RIMS3 and RIMS4 were implicated autism risk factors." (PMID 30619482, 2018). "The second top-ranked clique (hereafter will be referred as Clique II) included the autism genes: Rims3, and Astn2, and another four genes, all inter-connected at ≥79% co-expression level." (PMID 23935468, 2013). "Currently, it is suggested that RIMS3 is a gene related to autism." (PMID 36160034, 2022).
Parkinson disease (2 papers, 2013 to 2018). A progressive degenerative disorder of the central nervous system characterized by loss of dopamine producing neurons in the substantia nigra and the presence of Lewy bodies in the substantia nigra and locus coeruleus. "Agreeing with the role of alpha-synuclein at presynapses, several genes annotated for the Gene Ontology-slim term synapse showed differential expression, some of them previously associated with Parkinson's disease including Nptx2, Wnt7a, and Rims3." (PMID 29755323, 2018).
breast carcinoma (1 paper, 2022). "However, further studies are required to elucidate whether RIMS3, LOC283710, and ABCC6 genes are medium-impact putative passengers involved in the molecular pathways of carcinogenesis, leading to gastric cancer, breast cancer, or GIST." (PMID 35912179, 2022).
developmental delay (1 paper, 2016). "More precisely, GLUT1 deficiency may cause a specific syndrome which correlates with hyperactivity and developmental delay, RIMS3 is considered to be a novel candidate for autism, GRIK3 has also been associated with developmental delay, and AGO1/AGO3 may be responsible for neurocognitive deficits." (PMID 27713767, 2016).
tumor (4 papers, 2022 to 2023). "NGS analysis of the three tumors showed that three genes, namely, RIMS3, LOC283710, and ABCC6, with the same somatic mutation, were present in each tumor of the same individual." (PMID 35912179, 2022). "After detection, it was found that RIMS3 was significantly increased in normal samples, while SLC16A8 was substantially upregulated in tumor samples, which indicated that RIMS3 was a suppressor gene while SLC16A8 was an oncogene in CRC." (PMID 36160034, 2022). "Two of these, CKS2 and RIMS3, were shown to be substantially expressed in tumor tissues." (PMID 36733434, 2023). "Mutations in RIMS3, LOC283710, and ABCC6 genes do not cause tumor formation, suggesting that they might be passenger mutations." (PMID 35912179, 2022).
cancer (1 paper, 2021). A tumor composed of atypical neoplastic, often pleomorphic cells that invade other tissues. "RIMS3 is not reported to be associated with cancer to the best of our knowledge, and was likely a passenger event." (PMID 34805186, 2021).
RIMS3 also shares sentences with these, for which no sentence is quoted: epilepsy (1 paper); gastric cancer (1); genetic disorders (1); schizophrenia (1).